BRD1 (bromodomain containing 1)
Description:
Scaffold subunit of various histone acetyltransferase (HAT) complexes, such as the MOZ/MORF and HBO1 complexes, that acts as a regulator of hematopoiesis. Plays a key role in HBO1 complex by directing KAT7/HBO1 specificity towards histone H3 'Lys-14' acetylation (H3K14ac), thereby promoting erythroid differentiation.
Synonyms: BRL; BRPF2
Tractability: Small molecule: a structure with a bound ligand is known; a high-quality ligand is known; it has a binding pocket of medium quality. PROTAC: UniProt records ubiquitination sites on it; ubiquitination databases record sites on it; its protein half-life has been measured; a small molecule that binds it is known.
Target class: Epigenetic regulator; Bromodomain; Reader
Chemical probes: BAY-299 (high quality), NI-42, NI-57 (high quality), OF-1 (high quality)
Gene: Protein-coding gene on chromosome 22 (49,773,278 to 49,827,944, reverse strand). Ensembl gene ENSG00000100425.
Subcellular location: Nucleus; Chromosome
Subcellular location (Human Protein Atlas): Nuclear speckles
Pathways (Reactome):
Chromatin organization: HATs acetylate histones
Gene Ontology:
Molecular function: histone H3K14 acetyltransferase activity; histone H4K12 acetyltransferase activity; histone H4K5 acetyltransferase activity; histone H4K8 acetyltransferase activity; protein binding; unmodified histone reader activity; histone reader activity
Biological process: positive regulation of erythrocyte differentiation; regulation of developmental process; regulation of hemopoiesis; chromatin organization; chromatin remodeling; response to electrical stimulus; response to immobilization stress
Cellular component: chromosome; histone H3-K14 acetyltransferase complex; MOZ/MORF histone acetyltransferase complex; nuclear speck; nucleus; dendrite; perikaryon
Genetic constraint (gnomAD): Loss-of-function variants: 24 observed, 100.09 expected, observed/expected ratio (o/e) 0.24, 90% interval 0.17 to 0.34. The upper end of that interval is the gene's LOEUF score, 0.34, which puts it in group 1 of 6, group 1 being the genes least tolerant of losing a copy. Missense variants: 1,279 observed, 1,670.7 expected, observed/expected ratio (o/e) 0.77, 90% interval 0.73 to 0.8. Synonymous variants: 744 observed, 704.33 expected, observed/expected ratio (o/e) 1.06, 90% interval 0.99 to 1.12.
Homologues: Orthologues: chimpanzee BRD1 (99% identical), macaque BRD1 (98% identical), guinea pig BRD1 (95% identical), rat Brd1 (95% identical), pig BRD1 (91% identical), dog BRD1 (87% identical), mouse Brd1 (85% identical), tropical clawed frog brd1 (78% identical), rabbit BRD1 (78% identical), zebrafish brd1a (59% identical), zebrafish brd1b (54% identical), Drosophila melanogaster Br140 (39% identical), and 2 more. Paralogues in human: BRPF3 (53% identical), BRPF1 (51% identical), JADE1 (17% identical), JADE3 (17% identical), JADE2 (16% identical), MLLT10 (16% identical), PHF14 (15% identical), MLLT6 (14% identical).
Diseases named in the same sentence as BRD1 in open-access papers:
BRD1 is named in the same sentence as 27 diseases in open-access papers, as found by Europe PMC text mining. Sharing a sentence is not in itself a finding about the gene and the disease. The quoted sentences say what the papers report.
schizophrenia (13 papers, 2009 to 2023). A major psychotic disorder characterized by abnormalities in the perception or expression of reality. "The other gene identified in our study, BRD1, is associated with neuropsychiatric disorders such as schizophrenia and bipolar disorder along with its impact on neurodevelopmental disorders." (PMID 38002941, 2023). "Here we show that the schizophrenia and bipolar disorder associated epigenetic reader, BRD1, governs affective behaviors and associated neuromolecular and biological pathways in mice." (PMID 32681022, 2020). "The schizophrenia-associated gene, BRD1, encodes an epigenetic regulator in which chromatin interactome is enriched with genes implicated in mental health." (PMID 32681022, 2020). "Another bromodomain gene, BRD1, has been proposed as a susceptibility gene for both schizophrenia and BD42." (PMID 33168801, 2020). "In this study, we explore brain morphometry in mice with genetic susceptibility and phenotypic relevance to schizophrenia (Brd1+/− mice) using postmortem 3D MR imaging coupled with histology, immunostaining and regional mRNA marker analysis." (PMID 30405140, 2018). "This augmented previous studies linking rs138880 with both schizophrenia and bipolar disorders in large Caucasian case-control samples as well as the identification of a susceptibility locus containing BRD1 in the Faroese population." (PMID 28095495, 2017). "We also find that the schizophrenia-associated C allele of rs138880 not only correlates with slightly reduced BRD1 expression but also with moderately increased DNA methylation in BRD1 promoter regions in both adipose tissue and blood." (PMID 28095495, 2017). "Genetic variants in the BRD1 locus show association with schizophrenia and bipolar disorder and risk alleles in the promoter region correlate with reduced BRD1 expression." (PMID 28095495, 2017). "It has been suggested that upregulation of BRD1 is involved in stress resilience and response to antidepressants and reduced risk for schizophrenia." (PMID 28095495, 2017). "The bromodomain containing 1 (BRD1) gene has been implicated with transcriptional regulation, brain development, and susceptibility to schizophrenia and bipolar disorder." (PMID 27142060, 2016). "By interrogation of large datasets from genome-wide association studies, we further demonstrate that the BRD1 interaction network is enriched for schizophrenia risk." (PMID 27142060, 2016). "As the evidence for genetic association to the BRD1 locus is particularly strong in schizophrenia, we tested for enrichment in this disorder as our main analysis." (PMID 27142060, 2016). "Our findings indicate that BRD1 acts as a regulatory hub in a comprehensive schizophrenia risk network which plays a role in many brain regions throughout life, implicating e.g. striatum, hippocampus, and amygdala at mid-fetal stages." (PMID 27142060, 2016). "In summary, we identify the BRD1 interaction network to be enriched for schizophrenia risk thereby providing supporting evidence that BRD1 plays a role in the etiology of schizophrenia." (PMID 27142060, 2016). "The BRD1 locus approached genome-wide significance (P = 3.31 × 10–7) in the most recent schizophrenia genome-wide association study (GWAS) by the Psychiatric Genomics Consortium using conventional statistical methods." (PMID 27142060, 2016). "Bromodomain-containing protein 1 (BRD1), at chromosome 22q13, has recently been associated with schizophrenia and bipolar affective disorder." (PMID 19492091, 2009). "The BRD1 promoter SNP, rs138880, was recently identified as the variant showing the most significant association with schizophrenia in a large GWAS meta-analysis (>11,000 cases and >10,000 controls) ensued by a family-based replication study (>6,000 individuals including >3,000 cases)." (PMID 28095495, 2017).
schizophrenia (continued). "It has previously been suggested that BRD1 plays an important role in neurodevelopment and reduced levels of BRD1 could be a risk factor in schizophrenia with a pathogenic mechanism in line with the neurodevelopmental hypothesis of the disorder." (PMID 28095495, 2017). "Moreover, we interrogated large GWAS datasets and found that the BRD1 interaction network is enriched for schizophrenia risk." (PMID 27142060, 2016). "Interestingly, Brd1 has been implicated in the pathogenesis of schizophrenia and bipolar disorder." (PMID 34485298, 2021). "Among the genes, the bromodomain containing 1 (BRD1) gene has been shown to be associated with schizophrenia and bipolar disorder in genetic studies, including gene-wise significant association in a large schizophrenia genome-wide association study meta-analysis." (PMID 34777208, 2021). "Furthermore, in a schizophrenia GWAS meta-analysis (11,185 cases/10,768 controls) and a family-based replication study (3286 cases from 1811 families) the SNP rs138880 in the promoter region of BRD1 showed the overall most significant association." (PMID 27142060, 2016). "The Bromodomain containing 1 gene, BRD1, has been associated with mental illness in several genetic studies of common variants, including genome-wide association to schizophrenia (SZ)." (PMID 35941107, 2022). "Collectively, our study highlights the translational value of the Brd1+/− mouse as a pre-clinical tool for schizophrenia research and provides novel insight into its developmental, structural, and cellular pathology." (PMID 30405140, 2018). "In agreement with recent large-scale schizophrenia neuroimaging studies, Brd1+/− mice displayed subcortical abnormalities, including volumetric reductions of amygdala and striatum." (PMID 30405140, 2018). "Such dysregulation of BRD1 could adversely influence expression of several genes being important for normal brain development since BRD1 has been found to bind to the promoter regions and potentially regulate the transcription of a number of schizophrenia risk genes." (PMID 28095495, 2017). "We noticed that the BRD1 schizophrenia sub-network, across several spatiotemporal intervals, was more enriched with genes that co-expressed with BRD1 compared to other networks that included PTGs." (PMID 27142060, 2016). "The BRD1 schizophrenia sub-network comprised a significantly higher fraction of genes that co-expressed with BRD1 in 12 of the total 32 spatiotemporal intervals." (PMID 27142060, 2016). "When adjusting for the number of GWASs tested, significant enrichment was observed solely for the entire BRD1 network in schizophrenia (Padjusted = 0.03)." (PMID 27142060, 2016). "Furthermore, we identify spatiotemporal intervals in the human brain where BRD1 sub-networks are likely to play a role in brain function and schizophrenia." (PMID 27142060, 2016). "Moreover, the entire BRD1 network was more enriched with schizophrenia compared to the BRD1-S network, suggesting an enhanced effect of combining the networks from both isoforms." (PMID 27142060, 2016). "Interestingly, BRD1 that encodes bromodomain-containing protein 1, an essential cofactor of MOZ/MORF/HBO1 complexes, has been repetitively identified as a susceptibility gene for schizophrenia and bipolar disorder." (PMID 28161493, 2017). "Our finding that these proteins all interact with BRD1 provides a novel line of evidence implicating the network of BRD1, PBRM1, and 14-3-3 proteins with schizophrenia and bipolar disorder." (PMID 27142060, 2016).
bipolar disorder (10 papers, 2009 to 2023). A disorder of the brain that causes unusual shifts in mood, energy, activity levels and the ability to carry out day-to-day tasks. "Although the BRD1 interaction network was not identified to be enriched with bipolar disorder risk genes, it is reasonable to speculate that this difference is based on power constraints in the original GWAS rather than on a less prominent role of BRD1 in the etiology of bipolar disorder." (PMID 27142060, 2016).
mental disorder (6 papers, 2016 to 2026). A disease that has its basis in the disruption of mental process. "BRD1 is an epigenetic regulator implicated in neurodevelopmental and psychiatric disorders, yet its role in human neuronal differentiation, maturation, and function remains poorly understood." (PMID 41756449, 2026). "Bromodomain containing 1 (BRD1) encodes an epigenetic regulator that controls the expression of genetic networks linked to mental illness." (PMID 35941107, 2022). "This is particularly interesting in relation to neurodevelopment and mental disorders since BRD1 has been implicated in both." (PMID 28095495, 2017). "We present several novel protein interactions of BRD1, including isoform-specific interactions as well as proteins previously implicated with mental disorders." (PMID 27142060, 2016). "Although our studies specifically took its starting point in cell lines with well-characterized modulations of a psychiatric disorders risk gene, further validation of an association between BRD1 and mitochondrial dysfunction as well as its link to psychiatric disorders is warranted." (PMID 35941107, 2022). "We find that BRD1 primarily binds in close proximity to transcription start sites and regulates expression of numerous genes, many of which are involved with brain development and susceptibility to mental disorders." (PMID 27142060, 2016). "Using available GWAS datasets obtained from the Psychiatric Genomics Consortium (PGC) we investigated whether the BRD1 interaction network is enriched for mental disorder risk applying the MAGMA program." (PMID 27142060, 2016). "BRD1 encodes a scaffold protein that interacts with epigenetic modifiers affecting histone acetylation and histone H3 N-tail clipping and hereby modulates the transcription of a comprehensive set of genes implicated in brain development and mental disorder risk." (PMID 35941107, 2022). "In this study we have obtained results providing novel insights into the molecular interactions of BRD1 and its relation to mental disorders." (PMID 27142060, 2016). "Since mitochondrial modulators are emerging as an effective alternative treatment paradigm in psychiatric disorders, future studies in BRD1-based cell and mouse models should address both short- and long-term effects of such drugs as well as their underlying mechanisms of action." (PMID 35941107, 2022). "Chromatin profiling in neurons from SCZ patients has revealed aberrant roles for histone acetylation and BRD1, while BRD1-interaction networks show enrichment for SCZ risk genes and enhanced binding to gene promoters associated with brain development and mental disorders." (PMID 38476764, 2024).
Cognitive impairment (3 papers, 2020 to 2024). Abnormal cognition is characterized by deficits in thinking, reasoning, or remembering. "The expression of the epigenetic reader BRD1 increases after periods of chronic stress, and Brd1+/- mice display cognitive deficits and behavioral phenotypes." (PMID 38476764, 2024). "Neurons from Brd1+/− mice that do survive into adulthood have reduced dendritic arborization and spine density and aberrant spine morphology, phenotypes that have previously been linked to mitochondrial dysfunction and that could lead to cortical under-connectivity and cognitive impairments." (PMID 35941107, 2022).
breast carcinoma (2 papers, 2017 to 2019). "For example, several sex-ratio genes were found to interact with brc-1 and brd-1, the orthologs of the human breast cancer genes BRCA1 and BARD1, respectively." (PMID 28506208, 2017).
hepatocellular carcinoma (2 papers, 2022 to 2025). A malignant tumor that arises from hepatocytes. "The aberrant expression of BRD1 is frequently observed across a range of cancer types, including hepatocellular carcinomas (HCC)." (PMID 39962068, 2025). "In hepatocellular carcinoma, the expression of some BrD-family coding genes (BRD1/2/3/4/7/8/9) were significantly positively correlated with the immune-infiltrating degree of B cells, CD8+ T cells, CD4+ T cells, macrophages, neutrophils, and DCs." (PMID 36614001, 2022). "To elucidate the function role of BRD1 in the tumorigenesis of HCC, we first confirmed the expression status of BRD1 in liver hepatocellular carcinoma (LIHC) tissue." (PMID 39962068, 2025).
neuroblastoma (2 papers, 2012 to 2017). Neuroblastoma (NB) is the most common solid, extracranial childhood tumor. "We find that SH-SY5Y cells due to their origin (neuroblastoma) and neuronal characteristics represent a better model than HeLA cells to investigate whether brain directed drugs (mood stabilizers) would result in increased expression of BRD1 and associated changes in methylation." (PMID 28095495, 2017). "Using quantitative RT-PCR (qRT-PCR), we measured the endogenous expression of Zmynd8as, Brd1as, and the various isoforms of Zmynd8 and Brd1 in undifferentiated mESCs (UN), NPs (NP), and N2A (Neuro-2A), a mouse neuroblastoma cell line." (PMID 22937057, 2012).
Phelan-McDermid syndrome (2 papers, 2021 to 2022). A rare genetic neurodevelopmental disorder characterized by neonatal hypotonia, global developmental delay, normal to accelerated growth, absent to severely delayed speech, and minor dysmorphic features. "We identified the critical region including the BRD1 gene as responsible for the Phelan-McDermid syndrome epi-signature." (PMID 33407854, 2021). "Thus, BRD1 might be responsible for a phenotypically distinct clinical subtype of Phelan McDermid syndrome." (PMID 35941107, 2022).
Arthritis (1 paper, 2018). Inflammation of a joint. "Effects of BRD1 inhibition on other arthritis-relevant cell types in addition to SF and MDM are likely since BRD1 is expressed also in T- and B-cells." (PMID 30042400, 2018).
bone cancer (1 paper, 2020). A primary or metastatic malignant neoplasm affecting the bone or articular cartilage. "USP24 knockdown (KD) in H1299 lung cancer cells and U2OS bone cancer cells decreased levels of the BRD-containing proteins including BRG1, BRD7, BRD1, BRD3, GCN5, PCAF, and TIF1α." (PMID 33257797, 2020).
colorectal cancer (1 paper, 2022). A primary or metastatic malignant neoplasm that affects the colon or rectum. "BRD1 was significantly correlated with an unfavorable prognosis in colorectal cancer patients." (PMID 36276071, 2022).
depression (1 paper, 2020). "While equating Brd1 deficiency with depression susceptibility is over-simplistic, female Brd1+/− mice set the stage for further studies evaluating the epigenetic changes and neurodevelopmental abnormalities, pertinent to depression." (PMID 32681022, 2020). "Provided that the phenomenological and pathophysiological phenotype of female Brd1+/− mice indicate translational relevance to depressive disorders, they may be reversible upon the administration of clinically used antidepressants." (PMID 32681022, 2020).
dermatitis (1 paper, 2011). An inflammatory process affecting the skin. "In order to evaluate the anti-inflammatory effect of BrD1 on TPA-induced dermatitis in a murine model, we initially evaluated the possible inhibitory effect of BrD1 on TPA-induced vascular permeability." (PMID 22189182, 2011). "In the present study, we showed that a group of marine briarane-type diterpenes, particularly BrD1, can strongly suppress TPA-induced inflammation and dermatitis in a mouse skin model." (PMID 22189182, 2011). "The results from this study show that BrD1 can inhibit the activation of NF-κB in TPA-induced mouse dermatitis and in LPS-stimulated mouse BMDCs (data not shown)." (PMID 22189182, 2011).
prostate carcinoma (1 paper, 2024). A carcinoma that arises from epithelial cells of the prostate gland. "What’s more, our research demonstrated that specific genes, encompassing RNASEK, CPEB2, ARHGAP22, and BRD1, were enriched in the different cell clusters of prostate cancer tissues through the single-cell RNA sequencing localization analysis." (PMID 39600951, 2024).
renal carcinoma (1 paper, 2022). A carcinoma arising from the epithelium of the renal parenchyma or the renal pelvis. "Specifically, BRD1/2/3/4/7/8/9 proteins were analyzed in breast, liver, lung, ovarian, prostate, pancreatic, and renal cancer." (PMID 36614001, 2022).
serous ovarian cancer (1 paper, 2022). "Bromodomain-containing protein 1 (BRD1) is a negative regulator of T and NK cell activity in high-grade serous ovarian cancer (HGSC)." (PMID 36614001, 2022).